SETD1A (SET domain containing 1A, histone lysine methyltransferase)
Diseases named in the same sentence as SETD1A in open-access papers (continued):
Sharing a sentence is not in itself a finding about the gene and the disease.
breast cancer (25 papers, 2015 to 2026). A primary or metastatic malignant neoplasm involving the breast. "Furthermore, downregulation of EME1 was also observed when SETD1A was depleted from BRCA1-mutated HCC1937 breast cancer cells, or ATM-mutated H1395 lung cancer cells, suggesting that this represents a conserved mechanism in multiple cancer types." (PMID 39994444, 2025). "Related to cell cycle arrest prior to apoptosis in SETD1A KO GC cells, SETD1A depletion induces cell senescence in breast cancer cells." (PMID 40846851, 2025). "We first stratified lung adenocarcinoma, breast carcinoma or ovarian carcinoma patients by SETD1A mRNA expression and then assessed levels of each DEG." (PMID 39994444, 2025). "SETD1A has been found to promote tumors’ progression in various cancers, such as lung cancer, breast cancer, gastric cancer, colorectal cancer, and leukemia, by regulating TGF-β, Wnt, and Hippo/YAP signaling pathways." (PMID 37581938, 2023). "There is increasing evidence that the abnormal expression and activation of SETD1A promote cancer progression including gastric cancer, colorectal cancer, and breast cancer." (PMID 36707804, 2023). "SET Domain Containing 1A (SETD1A), which is upregulated in luminal breast cancer, promotes breast cancer proliferation, migration, and metastasis." (PMID 35453496, 2022). "Recent studies reported that SETD1A was highly expressed in hepatocellular carcinoma and breast cancer cells while high SETD1A results in sorafenib resistance." (PMID 36475064, 2022). "Previous studies have shown that SETD1A played a key role in embryonic stem cell self‐renewal and is required for breast cancer, lung adenocarcinoma, and colorectal cancer development." (PMID 32291851, 2020). "Clinicopathologic associations of SETD1A, a H3K4 methylator known to function as a transcriptional activator, have been reported in breast cancer." (PMID 33050946, 2020). "Moreover, and in agreement with preceding data, loss of SETD1A also restored Olaparib-induced RAD51 foci formation and thus HR activity in both BRCA1-mutated ovarian and breast cancer cell lines and in ATM-mutated lung cancer cells." (PMID 39994444, 2025). "We recently examined the function of SETD1A in tamoxifen-resistant breast cancer." (PMID 34201935, 2021). "Indeed, in tamoxifen-resistant breast cancer, SETD1A silencing dramatically reduces the expression of cell growth genes (e.g., EGFR and MYC) required for the development of tamoxifen resistance, and inhibits cell proliferation by inducing cell cycle arrest." (PMID 34201935, 2021). "In fact, amplification of the SETD1A gene in a high fraction (24%) of patient-derived breast cancer clones engrafting in mice could be attributed to the mitotic and cell cycle competence acquired by these high SETD1A expressing tumor cells." (PMID 31253781, 2019). "Similar to the brc-1 ortholog BRCA1, HORMAD1, SETD1A, KMT2C, and KM2D/MML4 have all been linked to breast cancer, suggesting that these genetic interactions may be conserved in human cells." (PMID 28506208, 2017). "SETD1A protein expression in cells increases in other BC subtypes, such as ER+, HER2+, and triple-negative breast cancer (TNBC) relative to healthy breast cells." (PMID 36188615, 2022). "SETD1A, an H3K4 methyltransferase, plays essential roles in multiple types of cancer progression including gastric cancer, colorectal cancer, and breast cancer, and liver cancer sorafenib resistance." (PMID 36707804, 2023). "As reported in a study, SETD1A activates MMP levels to modulate BC metastasis, and another study suggests that SETD1A amplification within mixed ductal and lobular breast cancer can upregulate the H3K4me3 marker to modulate mitosis within the mitosis and DNA damage response gene promoters." (PMID 36188615, 2022). "In breast cancer, its antitumor role is mediated by targeting of the SET domain-containing protein 1A (SETD1A)-PI3K-AKT pathway." (PMID 35549643, 2022).
breast cancer (continued). "Recent studies have also reported that upregulation of SETD1A can activate the PI3K/Akt pathway and promote breast cancer progression." (PMID 36475064, 2022). "SETD1A, a H3K4 methyltransferase, was upregulated and promoted cancer progression including colorectal cancer and breast cancer." (PMID 32291851, 2020). "To dissect the potential mechanisms underlying SETD1A-KD senescence, we performed transcriptome analysis using two different cell types (breast cancer MDA-MB-231 and lung cancer A549), in which SETD1A-KD induces senescence." (PMID 31253781, 2019). "SETD1A, a Set1/COMPASS family member maintaining histone-H3-lysine-4 (H3K4) methylation on transcriptionally active promoters, is overexpressed in breast cancer." (PMID 31253781, 2019). "Next, we performed quantitative RT-PCR (qRT-PCR) analysis to measure the mRNA expression level of eight HMTs (SETDB1, ASH1L, SMYD2, SMYD3, SETD1A, WHSC1L1, SUV420H1, and SETDB2) in 20 breast cancer cell lines." (PMID 25537518, 2015). "Notably, the intracellular protein levels of SETD1A are upregulated in other breast cancer subtypes, including ER-positive, HER2-positive, and TNBC breast cancer compared with normal breast cancer cells, and miR-1915-3p regulates this process." (PMID 34201935, 2021). "In addition, consistent with our findings in primary breast cancers, we also found that other HMTs, such as WHSC1L1, SUV420H1, and SETD1A, were commonly gained or amplified, and SETDB2 was commonly lost or deleted in breast cancer cell lines." (PMID 25537518, 2015). "While cytoplasmic localization is not considered the main form of occurrence of SETD1A and B proteins, it is not unprecedented and may even serve important functional purposes as observed in breast cancer." (PMID 38003223, 2023).
gastric cancer (15 papers, 2020 to 2025). A primary or metastatic malignant neoplasm involving the stomach. "The current study also showed that high level of SETD1A is positively associated with poor outcome, suggesting that SETD1A is positively correlated to gastric cancer." (PMID 32291851, 2020). "Aberrant SETD1A expression is associated with a poor prognosis in patients with gastric cancer (GC)." (PMID 40846851, 2025). "The H3K4-specific methyltransferase SETD1A plays a crucial role in gastric cancer; knockdown of SETD1A reduces lactate production and suppresses glycolysis by decreasing the expression of several glycolytic genes." (PMID 39062577, 2024). "Previous studies found that overexpression of SETD1A induced gastric cancer cell proliferation, while suppression of SETD1A attenuated the cell viability of gastric cancer cells." (PMID 36475064, 2022). "Most recently, SETD1A overexpression was also found in HIF1α-related gastric cancer, enhancing glycolysis and promoting gastric cancer progression." (PMID 34201935, 2021). "However, the function of SETD1A in gastric cancer (GC) progression and its role in GC metabolic reprogramming are still largely unknown." (PMID 32291851, 2020). "The third example involves the SETD1A/KMT2F that methylates H3K4 (me1, me2, and me3;) and promotes gastric cancer tumorigenesis by enhancing glycolysis, and by contributing to EMT regulation." (PMID 34681626, 2021).
leukemia (12 papers, 2016 to 2025). A malignant (clonal) hematologic disorder, involving hematopoietic stem cells and characterized by the presence of primitive or atypical myeloid or lymphoid cells in the bone marrow and the blood. "We propose targeting SETd1a in precision medicine as a new therapeutic approach for MLL1-associated leukemias." (PMID 39342993, 2024). "From a therapeutic standpoint, targeting the H3K4 trimethylation activity of the SETd1a complex may be a promising strategy for MLL1F-leukemias and other cancers with MLL1 mutations." (PMID 39342993, 2024). "Furthermore, we consistently identified missplicing (specifically intron retention) of key genes implicated in the pathogenesis of MLL-rearranged leukemia, namely SETD1A and DOT1L." (PMID 32398749, 2020). "We also performed ChIP-seq for SETD1B and SETD1A using HA-tagged SETD1B or SETD1A expressing MOLM-13 human MLL-r/FLT3-ITD leukemia cells." (PMID 40341256, 2025). "Instead, we advocate for a paradigm shift toward targeting SETd1a for inhibitor development as a more favorable approach to counteract abnormal H3K4 trimethylation in MLL1F leukemias." (PMID 39342993, 2024). "BOD1L knockout reduces leukemia cells in vitro and in vivo, and mimics the transcriptional profiles observed in SETD1A knockout cells." (PMID 38989615, 2024). "SETD1A is involved in cell proliferation in various cancers, including lung cancer, colorectal cancer, hepatocellular carcinoma, and leukemia, and in the development of resistance to anticancer drugs 60-67." (PMID 35966598, 2022). "We show that SETD1A degradation immediately downregulates heme biosynthesis pathway genes, which are required for functional cellular metabolism and leukemia cell proliferation." (PMID 36450243, 2022). "First, we transduced these vectors into mouse inducible Setd1a knockout MLL-r leukemia cells and established Setd1a knockout cells, which can grow with the replaced exogenous FKBP12F36V-HA-tagged SETD1A." (PMID 36450243, 2022). "Using the HA-tagged FKBP-SETD1A protein, we were able to detect chromatin binding of the exogenous SETD1A in the transduced leukemia cells." (PMID 36450243, 2022). "We compared our list of annotated genes that contained SETD1A peaks with those that were downregulated following dTAG-13 treatment and identified a list of 123 overlapping genes as the potential downstream targets of SETD1A in human leukemia cells." (PMID 36450243, 2022). "To investigate the roles of SETD1A-dependent metabolic regulation in leukemia cell proliferation, we performed metabolome analysis at 24 and 48 h post-dTAG-13 treatment in FKBP-SETD1A-expressing cells." (PMID 36450243, 2022). "In contrast, COX18, the other SETD1A-dependent complex IV assembly factor, was dispensable for leukemia cell growth as well as OCR." (PMID 36450243, 2022). "Importantly, intact genome-wide H3K4 methylation was observed in GC following SETD1A deletion, as observed in ES and leukemia cells." (PMID 40846851, 2025). "Thus, SETD1A regulates RNAP2 for the active transcriptional elongation of the genes associated with DNA repair and mitochondrial respiration in leukemia cells." (PMID 40846851, 2025). "Whether a similar redistribution of SETD1a and associated H3K4 trimethylation occurs on a genome-wide level in MT and MLL1F leukemia cells requires further investigation." (PMID 39342993, 2024). "In this study, we first established the PROTAC model of SETD1A in leukemia cell lines." (PMID 36450243, 2022). "Recently, the H3K4 methyltransferase SETD1A has been proposed to regulate the expression of genes involved in DNA damage response by interacting with cyclin K, and this interaction is required for leukemia cell growth." (PMID 33042275, 2020).
leukemia (continued). "Proximal labeling results showed that SETD1A and E2F4 closely localized to the chromatin in leukemia; however, their transcriptional activation functions have not been determined." (PMID 40846851, 2025). "To evaluate the effect of suppression of these SETD1A targets on mitochondrial oxygen consumption in leukemia cells, we measured the mitochondrial oxygen consumption rate (OCR) of sgRNA-expressing leukemia cells by flux analyzer." (PMID 36450243, 2022). "To validate the function of SETD1A target genes (COX15, HMBS, UROS, RRNAD1, NUDT18, GSTZ1, HINT2, and COX18) in leukemia cells, we performed a CRISPR-based competitive cell proliferation assay in doxycycline-inducible Cas9-expressing MOLM-13 leukemia cells." (PMID 36450243, 2022). "To evaluate the primary response of leukemia cells to SETD1A depletion, we constructed FKBP12F36V-HA-tagged SETD1A expression vectors." (PMID 36450243, 2022). "The non-catalytic function of SETD1A is to promote the expression of genes related to DNA repair in leukemia." (PMID 40846851, 2025). "In MLL-r leukemia, SETD1A assumes a non-catalytic role in the transcriptional elongation of genes crucial for DNA repair and mitochondrial respiration." (PMID 40341256, 2025). "The downregulation of COX15 expression by SETD1A disruption is also observed in non-MLL-r leukemia cell lines (U937 and K562) as well as sarcoma cell lines (A673 and RH30)." (PMID 36450243, 2022). "We used MLL-r leukemia cell lines for the SETD1A PROTAC model in this study but did not utilize them for in vivo assays." (PMID 36450243, 2022). "In leukemia with MLL-rearrangements, SETD1A is essential for cell proliferation." (PMID 34594227, 2021). "Loss of NCoR/SMRT localization, combined with relocalization of SETd1a, may underlie increased histone acetylation and H3K4 trimethylation in the absence of MLL1’s H3K4 dimethylation activity in MLL1F leukemias." (PMID 39342993, 2024). "In leukemia, the non-catalytic FLOS domain of SETD1A is necessary for cell survival and interacts with Cyclin K, a cofactor of CDK12/13 that phosphorylates RNAP2." (PMID 40846851, 2025). "Furthermore, small hairpin RNA knockdown of SETd1a but not SETd1b transcripts induces differentiation and apoptosis in murine and human MLL1F-leukemia cells." (PMID 39342993, 2024).
colorectal cancer (10 papers, 2007 to 2023). A primary or metastatic malignant neoplasm that affects the colon or rectum. "Previous studies have proven that SETD1A promotes Wnt/β-catenin pathway activity in colorectal cancer and neural progenitor cells." (PMID 34645486, 2021). "Additionally, SETD1A is overexpressed and promotes malignant phenotypes in many cancers, such as breast cancer, acute myeloid leukemia, colorectal cancer, gastric cancer, hepatocellular cell carcinoma and prostate cancer." (PMID 34645486, 2021). "Gene expression analysis of SETD1A in EBI Expression atlas revealed that SETD1A is downregulated in many cancers including triple-negative breast cancer, colorectal carcinoma and pancreatic adenocarcinoma." (PMID 32974170, 2020).
lung carcinoma (10 papers, 2015 to 2025). "In concert, these findings firmly establish that loss of SETD1A drives PARPi resistance in breast, ovarian and lung cancer cells by restoring HR." (PMID 39994444, 2025). "Firstly, we identified cohorts of HR-deficient breast, ovarian and lung cancer patients, stratified them by high/low SETD1A mRNA expression as before, and analysed overall survival rates." (PMID 39994444, 2025). "Indeed, SETD1A expression correlates with overall survival in HR-deficient breast, ovarian and lung cancers." (PMID 39994444, 2025). "Another study on lung cancer showed that SETD1A was upregulated and was a key epigenetic modification factor for NSCLC cell proliferation, its deletion inhibited DNA replication." (PMID 38164353, 2024). "In addition to its role in lung cancer, SETD1A also plays an important role in the progression of prostate cancer." (PMID 38164353, 2024). "The expression of SETD1A is significantly improved in lung cancer tissues." (PMID 36475064, 2022). "SETD1A encodes a subunit of the human Set/COMPASS complex (complex of proteins associating with Set1) and it might regulate multiple critical oncogenes in lung cancer via global H3K4me3 levels." (PMID 36475064, 2022). "In MDA-MB-231 as well as in A549 lung cancer cells and in DU145 prostate cancer cells, SETD1A depletion increased the G1 fraction (P<0.001, Student's t-test)." (PMID 26394836, 2015).
prostate carcinoma (9 papers, 2015 to 2025). A carcinoma that arises from epithelial cells of the prostate gland. "SETD1A, which is expressed at a higher level in mCRPC than in primary prostate cancer cells, promotes the expression of FOXM1, a gene encoding a cell proliferation-specific transcription factor." (PMID 32629770, 2020). "The MLL complex and its association with WDR5 shows that SETD1A also plays an important role in prostate cancer, especially in the progression of mCRPC." (PMID 32629770, 2020). "However, the functional contribution of SETD1A and its underlying mechanism in prostate cancer and mCRPC remains unclear." (PMID 32629770, 2020). "In a recent study, SETD1A is proven to promote cancer stem cell property and castration resistance of prostate cancer cells by activating FOXM1 transcription." (PMID 34645486, 2021). "The expression of SETD1A was significantly correlated with the survival rate of patients with prostate cancer." (PMID 32629770, 2020). "First, it was confirmed that SETD1A, which is involved in the growth of various prostate cancer cells, was overexpressed in mCRPC and activates FOXM1 signaling during the progression of mCRPC." (PMID 32629770, 2020). "Consistently, we observed that SETD1A silencing resulted in inhibition of the cell cycle in prostate cancer cell lines." (PMID 32629770, 2020). "We determined the expression of SETD1A in prostate cancer tissues and its relation with relapse-free survival (RFS)." (PMID 32629770, 2020). "Here, we investigated the effect of SETD1A expression on genes whose expression changes drastically during the development of mCRPC using prostate cancer cells." (PMID 32629770, 2020). "As SETD1A affects the growth of prostate cancer cells, we investigated whether SETD1A influences colony formation." (PMID 32629770, 2020). "In prostate cancer cells, SETD1A is reported to regulate cell cycle and tumor progression." (PMID 32629770, 2020). "We examined the expression of SETD1A in prostate cancer tissue." (PMID 32629770, 2020). "Thus, the regulation of FOXM1 expression by SETD1A suggests that SETD1A may play a key role in prostate cancer growth, metastasis, and castration resistance." (PMID 32629770, 2020). "Thus, targeting FOXM1 expression by inhibiting SETD1A may serve as a fundamental alternative to treating prostate cancer." (PMID 32629770, 2020). "The correlation between SETD1A and FOXM1 expression was verified in the human the prostate cancer gene expression data set." (PMID 32629770, 2020). "In test sets containing data of LNCaP and C4-2B (GSE107782), and other types of prostate cancer cell lines (GSE50936), we found that FOXM1 mRNA expression was significantly and positively correlated with that of SETD1A." (PMID 32629770, 2020). "We observed that the expression of both SETD1A and FOXM1 was increased in CRPC samples compared to that in primary prostate cancer in two independent clinical data sets." (PMID 32629770, 2020). "Besides, the expression of FOXM1 was promoted by SETD1A, which was expressed higher in CPRC than primary prostate cancer and facilitated stem cell factors and stem cell formation in metastatic CRPC." (PMID 35392496, 2022). "SETD1A is also essential for the expression of stem cell factors, e.g., octamer-binding transcription factor 4 (OCT4) and plays an important role in the proliferation of prostate cancer stem cells, which is important in metastatic CRPC tumor formation." (PMID 34201935, 2021). "Consistent with this hypothesis, we observed that growth of AR-dependent prostate cancer cells (LNCaP), as well as AR-independent prostate cancer cells (C4-2B, PC-3, DU145, and LNCaP-LN3), was significantly inhibited upon depletion of SETD1A in these cell lines using siRNA or shRNA." (PMID 32629770, 2020). "Presently, we demonstrated the mechanism by which SETD1A regulates the FOXM1 pathway and showed that it does not affect the AR pathway in prostate cancer cells." (PMID 32629770, 2020).